TNF (tumor necrosis factor)
Diseases named in the same sentence as TNF in open-access papers (continued):
Sharing a sentence is not in itself a finding about the gene and the disease.
psoriasis (continued). "A role for TNFα in Ccl20 expression has also been demonstrated in dermal lesions of psoriasis patients based on treatment with the TNFα antagonist infliximab." (PMID 24823369, 2014). "Currently the anti-psoriasis drugs, such as infliximab, have been widely used in prevention and treatment of TNF-α targeted prevention and treatment of psoriasis." (PMID 24718773, 2014). "TNF-α has multiple functions and is one of the most important proinflammatory cytokines in psoriasis, linking innate immunity to adaptive immunity." (PMID 25384035, 2014). "In a case report, the use of etanercept (TNF-alpha inhibitor) subcutaneously improved a patient affected by both psoriasis and vitiligo, although there was mild improvement of vitiligo." (PMID 24665368, 2014). "It was reported that clinical treatment of psoriasis patients with TNFα antagonists resulted in significant improvement of the epidermal barrier protein expression." (PMID 24686518, 2014). "Vascular endothelial growth factor (VEGF), one of the downstream molecules of EGFR and TNF signaling, plays a key role in angiogenesis for developing psoriasis." (PMID 25384035, 2014). "While pathogenesis of psoriasis has become better understood, tumor necrosis factor-α (TNF-α), IL-12, IL-23, and IL-17 seem to be critical checkpoints of psoriatic inflammation." (PMID 25759829, 2014). "A new zebrafish model of skin inflammatory disease explains new-onset and worsening psoriasis and lichen planus in patients receiving anti-TNFα therapy." (PMID 24802997, 2014). "TNF-α is produced by various cells in psoriasis, including keratinocytes, dendritic cells, macrophages and lymphocytes." (PMID 25384035, 2014). "In patient number 2 and number 26 methotrexate was added after starting TNF inhibitors due to a flare of arthritis and psoriasis, respectively." (PMID 24653837, 2014). "It is well known that TNF-α plays a critical role in the inflammation associated with RA, SLE, IBD, psoriasis and spondyloarthritis." (PMID 24968272, 2014). "Taken together, elevated levels and distribution of TACE and TNF-α in skin lesions of K5.Stat3C mice are similar to those in human psoriasis." (PMID 25384035, 2014). "Previous studies have shown that anti-TNF-α-based treatment induces an increase of Treg lymphocytes in patients with psoriasis." (PMID 25136144, 2014). "We also presented the effectiveness of anti-TNF agents for the top three indications: RA, CD, and psoriasis, but small sample size prevented us from performing additional statistical tests." (PMID 24883246, 2014). "The focus for therapeutic intervention in psoriasis is currently on modulating inflammatory immune parameters such as IL-17, IL-12, IL-23, or TNF, which are the immune drivers of skin pathology in both human disease and the mouse model." (PMID 24909886, 2014). "While pathogenesis of psoriasis has become better understood, tumor necrosis factor-α (TNF-α), IL-12, IL-23, and IL-17 seem to play key roles in the development of the immune response seen in psoriasis." (PMID 25614889, 2014). "TNF plays an essential role in the pathogenesis of psoriasis, but its mechanism of action is not fully understood." (PMID 24803721, 2014). "In conclusion, accumulating dermal infDC seem to play a key role in the progression of psoriasis and sustenance of psoriatic lesions by secreting large amounts of pro-inflammatory mediators including iNOS, IL-12/IL-23, and TNFα." (PMID 24744755, 2014). "One of the most typical examples of such paradoxical reactions regards the new onset of psoriasis in patients treated with anti-TNF-α therapy for chronic inflammatory diseases as RA, inflammatory bowel disease, and AS." (PMID 24600322, 2014). "So far, the experience with IL-6 inhibitors in psoriasis is limited, as other signaling pathways have been successfully investigated as therapeutic targets (i.e., TNF-alpha, IL-23, and IL-17)." (PMID 25126586, 2014).
psoriasis (continued). "Following effective therapy in psoriasis, TNFα, iNOS, and IL-23 production by Tip-DC is strongly reduced." (PMID 24744755, 2014). "Our attempt to model skin inflammation showed that the combination of IL-17A, IL-22, IL-1α, OSM and TNFα (Mix M5) synergistically increases chemokine and antimicrobial-peptide expression, recapitulating some features of psoriasis." (PMID 25010647, 2014). "Infliximab is a chimeric IgG1κ monoclonal antibody (composed of human constant and murine variable regions) specific for human TNF-α that inhibits the TNF-α-mediated production of IL-8 in psoriasis plaques." (PMID 24586752, 2014). "The high proportion of patients who were responders for RA, CD, and psoriasis provide some support for the effectiveness of anti-TNF agents at 12 months which parallels the results of other studies." (PMID 24883246, 2014). "A complex cytokine network has been described in psoriasis and highlighted a central role of proinflammatory cytokines such as IL-23, IL-22, IL-17, IL-1 or TNFα produced by infiltrated immune cells." (PMID 25010647, 2014). "This cytokine has a crucial role in psoriasis pathogenesis, as demonstrated by the efficacy of TNFα-targeted therapeutics." (PMID 24686518, 2014). "TNF-α inhibitors (anti-TNFs) have transformed the treatment paradigm of autoimmune diseases such as RA, psoriasis, PsA, AS and IBD, where standard systemic agents have failed." (PMID 23946436, 2014). "It has been demonstrated that TNF-α is involved in the development of psoriasis, as evidenced by the therapeutic efficacy of TNF-α inhibitors on psoriasis." (PMID 25384035, 2014). "Tumor necrosis factor (TNF) has been linked with autoimmune disorders, notably the TNF-inducible protein A20, which has been associated with RA, psoriasis, and SLE." (PMID 24900918, 2014). "By antagonizing TNF-α (increased in psoriasis), infliximab inhibits the release of proinflammatory cytokines and reduces the aberrant growth and proliferation of keratinocytes." (PMID 25870666, 2014). "TNF-α can synergize with IL-17 to promote inflammation in psoriasis and also IL-17 and IFN-γ synergize in pro-inflammatory cytokine production in keratinocytes." (PMID 25153527, 2014). "LC depletion was associated with an increase in the frequency of epidermal immune cells known to be key mediators in psoriasis such as neutrophils, or Lanneg APCs, that are efficient producers of TNF-α in psoriasis." (PMID 25216727, 2014). "Tumour necrosis factor alpha (TNFα) is a major proinflammatory cytokine in many chronic inflammatory diseases, including psoriasis." (PMID 24558628, 2013). "For CD8+ T cells, we observed that the production of IL-17A, IL-22, IFN-gamma, TNF-alpha, and IL-2 were higher in lesional skin than unaffected skin of psoriasis patients." (PMID 23468834, 2013). "Significant decrease of MMP-9 and MMP-2 levels in the sera was associated with clinical improvement and with the decrease of TNF-α, VEGF, and E-selectin, angiogenic molecules already known to be implicated in clinical expression of psoriasis." (PMID 24396598, 2013). "Cytokines involved in psoriasis, PsA, and diabetes include tumor necrosis factor-alpha (TNF-α), IL-1, and IL-6." (PMID 23843781, 2013). "Baseline testing of ANA and anti-dsDNA in all psoriasis patients prior to commencing TNFα inhibitors therapy are recommended." (PMID 24558628, 2013). "The inflammatory response in psoriasis is characterized by production of TNFα and production of IL1β." (PMID 24069534, 2013). "Recently it has been reported that IL-17A in combination with TNF-α synergistically induced many psoriasis-related immune response genes including several cytokines and chemokines as well as AMP such as psoriasin and hBD-2." (PMID 23555696, 2013). "A 52-year-old Japanese woman with a 12-year history of psoriasis started anti-TNF-α therapy with adalimumab for exacerbation of skin lesions." (PMID 24082887, 2013).
psoriasis (continued). "We present a case of AGEP, following administration of etanercept, an antitumour necrosis factor alpha (TNF-α) antibody, in a patient with psoriasis." (PMID 23573431, 2013). "Th17 cells producing IL-17, IL-22, and tumor necrosis factor-α are pathogenically related to psoriasis." (PMID 23365685, 2013). "T cells are the target of cyclosporine and DAB389-IL2, and TNF-α is the target of effective anti-cytokine biologics in psoriasis, thus validating the potential importance of gene expression signals observed in this range." (PMID 23308107, 2013). "A 52-year-old Japanese woman with psoriasis developed liver damage two months after initiation of anti-TNF-α therapy with adalimumab." (PMID 24082887, 2013). "It is on that basis, we discovered that curcumin can suppress inflammation in IMQ-induced psoriasis-like mice model and decrease the cytokines production, such as IL-17A, IL-17F, IL-22, IL-1β and TNF-α." (PMID 23825622, 2013). "Many immune-derived cytokines, including IL-23, IL-17A, IL-20, IL-22, IL-1β, IL-6, and TNF-a, are involved and interact as a network in the pathogenesis of psoriasis." (PMID 23825622, 2013). "This combination was more effective in inducing RNase 7 than the combination of IL-17A/TNF-α, a combination previously identified as a strong inducer of psoriasis-related immune response genes including several AMP." (PMID 23555696, 2013). "The findings from the meta-analysis provided a strong evidence for the important role of TNF-α 308 G/A polymorphism in the development of psoriasis, and TNF-α 308 G/A mutant allele A had a protective effect on psoriasis risk." (PMID 24324571, 2013). "The down-regulation of follicular PRLR expression by TNFα is also intriguing in view of the importance of TNFα in both inflammatory dermatoses such as psoriasis and hair growth." (PMID 23626671, 2013). "The use of agents that block the action of TNFα (infliximab, etanercept, and adalimumab) has shown clear benefits in the treatment of patients with inflammatory diseases such as psoriasis." (PMID 24069534, 2013). "Doxycycline-inducible human TNFα–transgenic mice developed an inflammatory arthritis– and psoriasis-like phenotype, with fore and hind paws being prominently affected." (PMID 23740547, 2013). "The women developing psoriasis after 40 years of age (n = 15) in turn showed over-expression of the following markers: TNF-308A (66.7% versus 22%." (PMID 23690822, 2013). "The cytokines produced by these cells, such as tumor necrosis factor-α (TNFα), interferon-γ (IFNγ), IL-17, IL-22, IL-23, IL-12 and IL-1β, create an inflammatory cascade, contributing to the pathogenesis of psoriasis." (PMID 24386404, 2013). "Apremilast is a PDE4 inhibitor that increases levels of cyclic adenosine monophosphate (cAMP), which activates the protein kinase A and modulates the cytokines involved in the immune response of psoriasis (decreases TNFα, IL23, and IFNγ and increases IL10)." (PMID 24069534, 2013). "Sixteen case-control studies with a total of 2,253 psoriasis cases and 1,947 controls on TNF-α 308 G/A polymorphism and fourteen studies on TNF-α 238 G/A polymorphism with 2,104 cases and 1,838 controls were finally included into the meta-analysis." (PMID 24324571, 2013). "Recent characterization of psoriasis immuno-pathophysiology showed that cytokines, in particular tumor necrosis factor (TNF), interleukin-12 (IL-12) and interleukin-23 (IL-23) represent therapeutic targets." (PMID 22509259, 2012). "Clinical applicability of QFT-IT has been prospectively assessed in 50 patients with psoriasis along with TST while patients were on anti-TNF therapy." (PMID 22645622, 2012). "Therefore, risk of malignancy with anti-TNF-α in psoriasis remains unclear." (PMID 22645622, 2012). "Similar findings are reported in other autoimmune diseases, and the TNF-α inhibitor etanercept was shown to relieve fatigue in a cohort of psoriasis patients." (PMID 22253903, 2012).
psoriasis (continued). "Several other TNF-α blockers have been developed and approved since then for other diseases, e.g. ankylosing spondylitis and psoriasis." (PMID 22737386, 2012). "The development of anti-TNFα therapies, which target a specific cytokine of the immune system, has dramatically changed the treatment of psoriasis and psoriatic arthritis over the last years." (PMID 22649467, 2012). "TNF and iNOS-producing DCs (TIP-DCs) are considered to be a subset of inflammatory myeloid DCs in psoriasis, and there were abundant TNF and iNOS producing cells (yellow cells) in lesional tissue at relapse." (PMID 22348003, 2012). "Psoriasis is a chronic inflammatory skin disorder which is characterized by local and systemic escalation of proinflammatory cytokines such as IL-6 and TNF-α." (PMID 22654590, 2012). "Compared with those in both healthy controls and psoriasis controls, the circulating concentrations of TNF-α, RANKL and OCs in patients with PsA were higher, but the ratio of OPG/RANKL were significantly lower." (PMID 23144698, 2012). "In fact, IL-17A, IL-22, and IL-23 are elevated in psoriatic skin, and IL-17A together with TNFα induces the expression of genes involved in psoriasis in human keratinocytes." (PMID 22229105, 2012). "Psoriasis (except palmo plantar pustular type) was the most common adverse effect during anti-TNF-α treatment (n=73), followed by palmoplantar pustular psoriasis (n=37) and psoriasis of the nail (n=6), sometimes combined in the same patient." (PMID 23071483, 2012). "LLS was only detected in a patient with a history of psoriasis since youth, who developed psoriatic arthritis after 27 years of age and had received anti-TNFα therapy for > 2 years." (PMID 22336076, 2012). "Transgenic mice expressing the caspase-cleaved form of the tyrosine kinase Lyn (LynΔN) develop a TNFα-dependent skin disease that accurately recapitulates human psoriasis." (PMID 23071785, 2012). "In these models, we finally analyzed the effects of the change from IL-17 (Th17, psoriasis) to IL-4/IL-13 (Th2, AD), in the same cytokine background (TNFα and IL-22)." (PMID 23193414, 2012). "Applying LTBI diagnosis guidelines, latent infection resulted in more psoriasis (50%) than inflammatory bowel disease patients (24.2%), prior to onset of any anti-TNF-α treatment (P = 0.04)." (PMID 22645622, 2012). "Migration of epidermal Langerhans cells (LCs) in response to the cytokines interleukin (IL)-1β and tumour necrosis factor (TNF)-α is impaired in uninvolved skin of patients with early-onset psoriasis." (PMID 21933242, 2012). "We reported previously that LynΔN mice exhibited very early after birth a TNFα-dependent cutaneous syndrome that recapitulates accurately human psoriasis." (PMID 23071785, 2012). "There are two possibilities: either each patient with psoriasis must receive chemoprophylaxis before starting anti-TNF therapy, or other tests should be used." (PMID 27536430, 2012). "Our data showed that the circulating concentrations of TNF-α in patients with PsA were higher than those in both healthy controls and psoriasis controls." (PMID 23144698, 2012). "These in vitro and in vivo observations are confirmed by numerous clinical studies of successful anti-TNF therapy in psoriasis since the first report in 2000." (PMID 23193414, 2012). "Proinflammatory cytokines that are up-regulated in psoriasis include tumor necrosis factor alpha (TNFα), interleukin-12 (IL-12), and IL-23 for which monoclonal antibodies have already been approved for clinical use." (PMID 21352568, 2011). "In psoriasis elevated TNF levels have been measured in serum and in the epidermis of psoriatic plaques [and references therein]." (PMID 22074550, 2011). "For example, several inhibitors of tumor necrosis factor alpha (TNFα), which is considered one of the primary mediators of immune regulation, have been developed and proven successful in psoriasis treatment." (PMID 21352568, 2011).
psoriasis (continued). "We therefore evaluated the expression of selected cytokines and chemokines thought to contribute to initiation or maintenance of the inflammatory cascade in human psoriasis (e.g., TNF, IL22, IL6, CXCL1)." (PMID 21483750, 2011). "It regulates the transcription of many important mediators of inflammation and tissue destruction in the psoriasis including TNF, IL-1 and IL-6." (PMID 22125590, 2011). "We have previously shown that TNFα mRNA knockdown in the psoriasis xenograft transplantation model has a significant positive effect on the clinical psoriatic phenotype throughout the treatment course." (PMID 21352568, 2011). "Psoriasis is associated with over-expression of T-helper cell type 1 (Th1) cytokines, IFN-γ and TNF-α in the involved skin and relative underexpression of T-helper cell type 2 (Th2) cytokines, interleukin IL-4 and IL-10." (PMID 21152006, 2010). "As it is a T cell mediated disorder, clinical trials are underway with agents attempting to suppress the “inflammation characteristic” of psoriasis targetting TNF-alpha and other proinflammatory cytokines, T cell activation and lymphocyte trafficking." (PMID 21063523, 2010). "We recently conducted a clinical trial of 15 psoriasis patients with the TNF inhibitor etanercept, and performed a time-course experiment using HGU 133 2.0 microarray chips." (PMID 20422035, 2010). "TNFα is produced by skin antigen-presenting cells and by keratinocytes during psoriasis progression and stands out as one of several central cytokines in the pathogenesis of the disease." (PMID 20594301, 2010). "For example, we used the time slope of a mixed effect model as a phenotype to evaluate the time-response of cytokines pathways to psoriasis treatment with TNF inhibitor." (PMID 20422035, 2010). "In accordance, the expression of several cytokines assumed to play a role in the pathogenesis of psoriasis (i.e. IL-20, TNF, IL-8, and IL-6) are p38 MAPK-regulated." (PMID 20072629, 2010). "This complexity and redundancy of psoriasis signaling likely contributes to the inefficiency of current treatments, even novel therapies such as monoclonal antibodies against TNF-α and IL-23." (PMID 20377895, 2010). "Adalimumab, a fully human monoclonal antibody that binds to and neutralizes TNF, is approved for the treatment of AS, PsA, RA, psoriasis, juvenile idiopathic arthritis, and Crohn disease in Europe, Canada, the United States, and other world regions." (PMID 20553600, 2010). "By intradermal injection of a single dose of lentiviral vectors encoding TNFα-targeted shRNAs, we measured a reduction in the levels of TNF-α mRNA in transplanted skin and observed both clinical and histological improvements of the psoriasis phenotype." (PMID 20594301, 2010). "More recently, systemic administration of such inhibitors of TNFα has been established as a potent treatment of severe psoriasis." (PMID 20594301, 2010). "Inhibitors of TNFα as an absolute key player have been applied to psoriasis in animal models and/or patients with great success." (PMID 20594301, 2010). "In the present study, we compared cell proliferation induced by various cytokines and growth factors as well as TNF-α-induced secretion of cytokine/growth factors among keratinocytes from normal skin, uninvolved, and involved psoriasis." (PMID 20161853, 2009). "The development of TNF alpha blocker biologics for the treatment of psoriasis, psoriatic arthritis, RA, Crohn's disease, and ankylosing spondylitis is a major breakthrough in the treatment for autoimmune diseases." (PMID 20101303, 2009). "Treatment of patients with TNFα-blocking therapeutic agents dramatically improved symptoms of arthritis and psoriasis." (PMID 22399974, 2009). "Currently, the biologics approved by the US Food and Drug Administration to treat psoriasis target either T cells or TNF-α." (PMID 18648529, 2008).